HNRNPU (heterogeneous nuclear ribonucleoprotein U)
Diseases named in the same sentence as HNRNPU in open-access papers (continued):
Sharing a sentence is not in itself a finding about the gene and the disease.
microcephaly (10 papers, 2015 to 2023). A congenital or acquired developmental disorder in which the circumference of the head is smaller than normal for the person's age and sex. "In contrast, data from patients with HNRNPU mutations shows that heterozygous loss of HNRNPU is rarely associated with microcephaly." (PMID 28283832, 2017). "AKT3 (1q43-q44; MIM 611223) deletions lead to partially penetrant microcephaly although the contribution of ZBTB18 (1q44; MIM 608433) and HNRNPU (1q44; MIM 602869) mutation is possible." (PMID 32916978, 2020). "Furthermore, HNRNPU+/− hCOs resulted in a significant size reduction, consistent with both evidence of microcephaly in a subset of patients and size reduction across several mouse models of HNRNPU-related disorder." (PMID 36594023, 2023). "However, because ofthe presentation of microcephaly in the patients with intactAKT3 gene, the other candidate genes such as NLRP3,HNRNPU, SMYD3, and KIF26B have been suggestedto cause microcephaly." (PMID 31210441, 2019). "An other splicing factor, HNRNPU, which we identified to co-purify with CSB-TAP, when mutated gives rise to clinical features that are shared by CS patients: microcephaly, developmental delay, hearing loss, vertebral anomalies and characteristic facial features." (PMID 26030138, 2015). "A de novo deletion at 1q44q44 spanning HNRNPU and ZBTB18 has been described in cases with ID, EP, microcephaly, and hypogenesis of the corpus callosum." (PMID 30510536, 2018). "The first encompassing ZNF238 was associated with corpus callosum anomalies (CCA) and the second includes AKT3 with microcephaly (MIC), while the third contains the two coding genes FAM36A, HNRNPU and the noncoding gene NCRNA00201 with seizures." (PMID 25722899, 2015). "The alignments of microdeletions found in patients with a known OFC and comparison of their gene content showed that microcephaly was present in all 20 patients with deletions encompassing both AKT3 and ZBTB18, regardless of the presence of HNRNPU in the deletions." (PMID 28283832, 2017).
gastric cancer (9 papers, 2021 to 2026). A primary or metastatic malignant neoplasm involving the stomach. "Additionally, hnRNPU is a well‐established RNA‐binding protein that has been widely implicated in the regulation of alternative splicing (AS) in various cells, such as cardiomyocytes and gastric cancer cells." (PMID 41524182, 2026). "In summary, we have demonstrated that circ-hnRNPU is down-regulated in gastric cancer, and closely related to favorable outcome of patients." (PMID 37993881, 2023). "Lower circ-hnRNPU levels were observed in gastric cancer specimens, when compared with normal gastric mucosa, especially in those of advanced clinical stages, which were associated with poor survival probability of patients (P < 1.0 × 10–4)." (PMID 37993881, 2023). "Among them, only hsa_circ_0112825 (termed as circ-hnRNPU) was detectable in gastric cancer AGS cells, which was further validated by amplification using convergent or divergent primers." (PMID 37993881, 2023). "Since protein glycosylation contributes to tumorigenesis and aggressiveness, we further investigated the influence of circ-hnRNPU on biological behaviors of gastric cancer cells." (PMID 37993881, 2023). "There was decreased circ-hnRNPU expression in gastric cancer cell lines (AGS, MGC-803, MKN-45, and NCI-N87), prostate cancer PC-3 cells, and cervical cancer HeLa cells, when compared to that of GES-1 cells." (PMID 37993881, 2023). "The RNase R resistant characteristics were further observed in endogenous and exogenous circ-hnRNPU, which was mainly localized at cytoplasm of gastric cancer cells." (PMID 37993881, 2023). "Pre-clinically, administration of lentivirus carrying circ-hnRNPU suppressed the protein glycosylation, tumorigenesis, and aggressiveness of gastric cancer xenografts." (PMID 37993881, 2023). "HNRNPU is a possible marker for the diagnoses of multiple cancers, including pancreatic ductal adenocarcinoma, nasopharyngeal carcinoma, gastric cancer, and clear cell renal cell carcinoma." (PMID 35130920, 2022). "Importantly, stable ectopic expression or silencing of circ-hnRNPU led to significant reduction or elevation of O- and N-glycosylation in gastric cancer AGS and NCI-N87 cells." (PMID 37993881, 2023). "Circ-hnRNPU, an exonic circRNA derived from heterogenous nuclear ribonuclear protein U (hnRNPU), was identified to exert tumor suppressive roles in protein glycosylation and progression of gastric cancer." (PMID 37993881, 2023). "In this study, we identify one circRNA derived from hnRNPU (circ-hnRNPU) as a tumor suppressor significantly down-regulated in gastric cancer, which inhibits the glycosylation, proliferation, invasion, and migration of gastric cancer cells." (PMID 37993881, 2023). "This study demonstrates that aberrant alternative splicing plays a critical role in gastric cancer (GC) progression, with hnRNPU emerging as a key modulator of this process." (PMID 39773744, 2025). "In this study, we identify a circRNA derived from exons 5, 6, 7 and 8 of heterogeneous nuclear ribonucleoprotein U (hnRNPU), an oncogene with multiple important functions, which is termed as circ-hnRNPU that acts as a tumor suppressor in glycosylation and progression of gastric cancer." (PMID 37993881, 2023). "Similarly, high hnRNPU levels are also observed in gastric cancer tissues and predict poor prognosis in gastric cancer patients, suggesting that hnRNPR and hnRNPU may be tumor-promoting factors in gastric cancer cells." (PMID 35875075, 2022). "CircSLC22A23 promotes gastric cancer cell proliferation, migration, and invasion by participating in the regulation of epidermal growth factor receptor (EGFR) transcription through the activation of HNRNPU protein expression." (PMID 40708910, 2025). "Similar to hsa_circ_0003611, circ-hnRNPU binds with non-POU domain containing octamer binding (NONO) protein to decrease MYC mRNA stability in gastric cancer cells." (PMID 41318550, 2025).
gastric cancer (continued). "There was significantly elevated cytoplasmic NONO expression in gastric cancer specimens with high circ-hnRNPU levels." (PMID 37993881, 2023). "In clinical cases, low circ-hnRNPU levels and high NONO or c-Myc expression were associated with poor survival outcome of gastric cancer patients." (PMID 37993881, 2023). "Rescue studies indicated that circ-hnRNPU inhibited the N- and O-glycosylation, growth, invasion, and metastasis of gastric cancer cells via interacting with NONO protein." (PMID 37993881, 2023). "In addition, circ-hnRNPU inhibits glycosylation, growth, invasion, and metastasis of gastric cancer cells via interacting with NONO protein, providing a therapeutic target for protein glycosylation and cancer progression." (PMID 37993881, 2023). "Importantly, as a RBP, cytoplasmic NONO stabilizes GALNT2, GALNT6, and hnRNPU mRNA in gastric cancer cells, which is also repressed by circ-hnRNPU." (PMID 37993881, 2023). "In these gastric cancer cases, the expression of circ-hnRNPU, NONO, or c-Myc was negatively or positively correlated with that of target genes GALNT2, GALNT6, MGAT1, or hnRNPU." (PMID 37993881, 2023). "Next, we further investigated the functions of circ-hnRNPU and NONO in gastric cancer progression." (PMID 37993881, 2023). "We believe that this study extends our knowledge about the regulation of glycosyltransferase and hnRNPU expression by circRNA and its protein partner, and suggests that circ-hnRNPU/NONO/c-Myc axis may be a potential therapeutic target for gastric cancer." (PMID 37993881, 2023).
bladder cancer (8 papers, 2022 to 2025). "Moreover, hnRNPU expression was associated with cisplatin sensitivity in bladder cancer." (PMID 35954396, 2022). "We identified HNRNPU as another important interacting protein of FAM171B in the nucleus of bladder cancer cells." (PMID 37915048, 2023). "Collectively, these findings highlight vimentin and HNRNPU as the primary interacting proteins of FAM171B in bladder cancer cells." (PMID 37915048, 2023). "Immunoprecipitation using anti-DYKDDDDK and anti-HA beads confirmed the interactions of FAM171B with vimentin and HNRNPU in MB49 mouse bladder cancer cells." (PMID 37915048, 2023). "Our previous results demonstrated that HNRNPU is an important interacting protein of FAM171B in bladder cancer cells." (PMID 37915048, 2023). "In a panel of bladder cancer cell lines, a significant correlation was found between HNRNPU protein level and the cytotoxicity of cisplatin." (PMID 35130920, 2022). "We also observed a more hypomethylated promoter of the HNRNPU gene in bladder cancer tissues from the TCGA dataset, compared to the normal bladder tissues." (PMID 35130920, 2022). "Using the GEPIA2021 deconvolution tool for the TCGA bladder cancer cohort, we found that HNRNPU was significantly decreased in B cells, CD4+ T cells, and CD8+ T cells." (PMID 35130920, 2022). "We examined the overall expression level of HNRNPU in the TCGA bladder cancer cohort (T = 404) and found that HNRNPU was highly expressed in bladder tumors, compared to normal tissues." (PMID 35130920, 2022). "On the other hand, higher levels of mRNA HNRNPU were observed in tumoral vs. adjacent tissue in breast, hepatocellular, and bladder cancers." (PMID 36242708, 2022). "Moreover, we validated the interactions between FAM171B and vimentin/HNRNPU in MB49 bladder cancer cells from mice." (PMID 37915048, 2023). "Furthermore, we demonstrated that knockout of HNRNPU in combination with cisplatin treatment induced apoptosis, S-phase arrest, and inhibited cell migration in a cisplatin-resistant bladder cancer cell line." (PMID 35130920, 2022). "Knocking out HNRNPU enhanced cisplatin sensitivity by regulating DNA damage repair genes, suggesting that targeting HNRNPU could offer a potential therapeutic approach for cisplatin-resistant bladder cancer." (PMID 38003514, 2023). "Inhibition of HNRNPU could be a potential therapy for cisplatin-resistant bladder cancer." (PMID 35130920, 2022). "To explore the effect of FAM171B and HNRNPU on macrophage chemotaxis, we cocultured RAW264.7 mouse macrophages with different groups of MB49 mouse bladder cancer cells." (PMID 37915048, 2023). "In this study, we found that HNRNPU is involved in the response of bladder cancer to cisplatin, but not doxorubicin or paclitaxel in vitro." (PMID 35130920, 2022).
hepatocellular carcinoma (7 papers, 2014 to 2025). A malignant tumor that arises from hepatocytes. "Evidence indicates that HNRNPU knockdown in hepatocellular carcinoma cells inhibits cell growth and decreases chromatin accessibility." (PMID 36242708, 2022). "HNRNPU is overexpressed in hepatocellular carcinoma (HCC) and promotes HCC occurrence and progression." (PMID 35892886, 2022).
developmental delay (6 papers, 2015 to 2026). "Except one, all patients with 1q43q44 microdeletions or point mutations in ZBTB18 and HNRNPU had developmental delay or ID with a wide range of severity." (PMID 28283832, 2017). "In lineage 2, risk genes associated with developmental delay, such as ZBTB20 and HNRNPU, were highly expressed at the initial stage." (PMID 39363111, 2024). "Because patients with HNRNPU haploinsufficiency often have autistic features, developmental delay, and seizures, we next tested for the enrichment of genes associated with these conditions among each population of cells." (PMID 37782669, 2023).
Epileptic encephalopathy (6 papers, 2014 to 2025). A condition in which epileptiform abnormalities are believed to contribute to the progressive disturbance in cerebral function. "Heterozygous de novo loss-of-function mutations in the gene expression regulator HNRNPU cause an early-onset developmental and epileptic encephalopathy." (PMID 37782669, 2023). "All three of our recontacted patients with HNRNPU variants present with seizures, consistent with its association with epileptic encephalopathy and DD28." (PMID 33004838, 2020). "Together with our study, these results support a conclusion that MBD5 and HNRNPU play an important role in the susceptibility to IS and epileptic encephalopathy." (PMID 24885232, 2014). "Representative examples include POLR1C (RNA polymerase dysfunction), TCF4 (Pitt–Hopkins syndrome), and HNRNPU (epileptic encephalopathy)." (PMID 41300846, 2025).
lung cancer (5 papers, 2015 to 2022). A malignant neoplasm involving the lung. "The present study aimed to investigate expression levels and prognostic significance of RUVBL1 and HNRNPU in stage I and II non–small-cell lung cancer (NSCLC) patients." (PMID 36242708, 2022). "The expression of XIST and co-regulated genes TSIX, hnRNPu, Bcl-2, and BRCA1 analyses in lung cancer (LC) and controls were performed in silico." (PMID 33255394, 2020). "Leveraging the available large-scale sequence data from TCGA and GTEX, we demonstrate that XIST, TSIX, hnRNPu, Bcl-2, and BRCA1 are differentially expressed in two different types of lung cancer when compared to controls." (PMID 33255394, 2020).
colon carcinoma (4 papers, 2019 to 2025). "Using Tissue Scan RT Colon Cancer Disease Panels III HCRT103 (OriGene, MD, USA), mRNA levels of hnRNPA1, hnRNPU, or TRA2β1 and TRA2β4 levels in 24 patients with colon cancers were measured by RT-qPCR." (PMID 31311954, 2019). "In addition, UALCAN database analysis showed that HnRNPU protein expression was increased in colon cancer tissues." (PMID 41310105, 2025). "This study looks at a protein called HnRNPU in colon cancer." (PMID 41310105, 2025). "Although this is the limited survey, these results suggest that hnRNPA1 and hnRNPU may contribute Tra2β overexpression in colon cancer cells." (PMID 31311954, 2019). "To investigate the biological function of HnRNPU in COAD, we examined its expression in various colon cancer cell lines." (PMID 41310105, 2025). "Another increased mRNA expression factor was hnRNPU with a fold change = 1.657 in patients with COAD, fold change = 1.900 in patients with colon carcinoma, and fold change = 2.151 in patients with rectal adenoma." (PMID 35875075, 2022).
developmental and epileptic encephalopathy, 54 (4 papers, 2021 to 2024). "To date, several reports exist about the pathogenic genetic variants affecting the HNRNPU gene in individuals with HNRNPU-related disorder, and are mostly de novo loss-of-function variants at sequence or copy number level." (PMID 37815090, 2023). "WES revealed a pathogenic missense mutation in the HNRNPU gene, associated with HNRNPU-related neurodevelopmental disorder (HNRNPU-NDD) and developmental and epileptic encephalopathy-54 (DEE54, OMIM: # 617391)." (PMID 38846959, 2024). "Developmental and epileptic encephalopathy 54 (DEE54; OMIM 617391) is caused by heterozygous mutation in HNRNPU, the gene encoding the RBP hnRNP U." (PMID 34564083, 2021). "Follow-up studies of direct targets, different developmental stages, and brain regions using both two-dimensional (2D) and organoid models will be needed to assess better the impact of HNRNPU haploinsufficiency on neurogenesis and its role in the pathogenesis of HNRNPU-related disorders." (PMID 37815090, 2023).
neuroblastoma (4 papers, 2014 to 2022). Neuroblastoma (NB) is the most common solid, extracranial childhood tumor. "Similarly, HNF4α has been shown to promote glycolysis, glucose uptake, lactic acid production and ATP levels in neuroblastoma cells, and the underlying mechanism involved hexokinase 2 (HK2) and Solute Carrier Family 2 Member 1 (SLC2A1) and the heterogeneous nuclear ribonucleoprotein U (hnRNPU)." (PMID 36249028, 2022).
melanoma (3 papers, 2019 to 2025). A malignant, usually aggressive tumor composed of atypical, neoplastic melanocytes. "We found that HNRNPU does localize to the cytoplasmic fraction by both subcellular fractionation and immunofluorescence analysis, and its steady state protein levels are also increased in melanoma cell lines relative to primary cells, consistent with those of RPS3." (PMID 34070332, 2021).
multiple myeloma (3 papers, 2023 to 2025). "Interestingly, recent studies show that hnRNPU-derived hsa_circ_0017272 is able to encode a protein consisting of 603 aa, which promotes the proliferation of multiple myeloma cells via regulating exon skipping of S-phase kinase associated protein 2 and stabilizing c-Myc protein." (PMID 37993881, 2023).
amyotrophic lateral sclerosis (2 papers, 2025). Amyotrophic lateral sclerosis (ALS) is a neurodegenerative disease characterized by progressive muscular paralysis reflecting degeneration of motor neurons in the primary motor cortex, corticospinal tracts, brainstem and spinal cord. "Among these genes, HNRNPA1, HNRNPC, and HNRNPU are involved in RNA processing and have been linked to neurodegenerative diseases such as amyotrophic lateral sclerosis and frontotemporal dementia." (PMID 40943121, 2025).
autism (2 papers, 2024 to 2026). Persistent deficits in social interaction and communication and interaction as well as a markedly restricted repertoire of activity and interest as well as repetitive patterns of behavior. "Among the most compelling genes were NR4A2 and HNRNPU, listed as ‘high confidence’ autism-associated genes in the SFARI database given the multiple separate reports identifying mutations in each of these genes in autistic people." (PMID 41507264, 2026).
Diabetic Nephropathy (2 papers, 2024 to 2025). "lncRNA EVF-2 upregulation interacts with hnRNPU, promoting podocyte cell cycle re-entry and inflammation in diabetic nephropathy." (PMID 41009556, 2025).
infantile epileptic encephalopathy (2 papers, 2018 to 2021). an epileptic condition characterized by epileptiform abnormalities associated with progressive cerebral dysfunction. "However, HNRNPU is a highly constrained gene for LOF variants, in which haploinsufficiency causes early infantile epileptic encephalopathy (EIEE [MIM: 617391])." (PMID 30526634, 2018).
infantile spasms (2 papers, 2014 to 2022). A rare epilepsy syndrome characterized by onset of epileptic spasms in infants between 2 and 12 months of age, and rarely up to 24 months. "Our findings thus provide further support that HNRNPU in the 1q44 region is pathogenic or causative gene for infantile spasms in this case." (PMID 24885232, 2014). "Mutations in HNRNPU have been associated with infantile spasms." (PMID 36180424, 2022). "Interestingly, a sequence variant at the splice acceptor site of HNRNPU was found in a patient with infantile spasms by whole exome sequencing (WES) in Epi4K project." (PMID 24885232, 2014).
pancreatic cancer (2 papers, 2025). "In conclusion, our study identifies TRIM9 as a key regulator of HNRNPU stability through K11-linked ubiquitination in pancreatic cancer." (PMID 41050689, 2025). "Our study contributes to this gap by providing evidence that TRIM9 exerts its effects on pancreatic cancer through its interaction with HNRNPU." (PMID 41050689, 2025). "Previous studies have suggested that HNRNPU plays a role in promoting tumor progression, yet the mechanisms by which its stability is controlled, particularly in the context of pancreatic cancer, remain unclear." (PMID 41050689, 2025). "HNRNPU is an RNA-binding protein that regulates alternative splicing, RNA stability, and transcriptional control, and has been shown to promote tumor cell proliferation and survival in various cancers, including pancreatic cancer." (PMID 41050689, 2025). "To test this hypothesis, we employed a variety of computational and experimental approaches, including single-cell RNA sequencing (scRNA-seq), spatial transcriptomics, and transcriptomic data analysis, to explore the expression patterns of TRIM9 and HNRNPU in pancreatic cancer." (PMID 41050689, 2025). "In the MIAPaca-2 pancreatic cancer cell line, overexpression of TRIM9 led to a reduction in the protein level of HNRNPU." (PMID 41050689, 2025).